SH2D4B (SH2 domain containing 4B)
Tractability: No criterion of Open Targets' tractability assessment is met for any kind of drug.
Gene: Protein-coding gene on chromosome 10 (80,537,902 to 80,646,560, forward strand). Ensembl gene ENSG00000178217.
Gene Ontology:
Molecular function: protein-macromolecule adaptor activity
Cellular component: cytoplasm
Genetic constraint (gnomAD): Loss-of-function variants: 45 observed, 56.46 expected, observed/expected ratio (o/e) 0.8, 90% interval 0.63 to 1.02. The upper end of that interval is the gene's LOEUF score, 1.02, which puts it in group 4 of 6, group 1 being the genes least tolerant of losing a copy. Missense variants: 572 observed, 553.66 expected, observed/expected ratio (o/e) 1.03, 90% interval 0.96 to 1.11. Synonymous variants: 224 observed, 208.19 expected, observed/expected ratio (o/e) 1.08, 90% interval 0.96 to 1.2.
Homologues: Orthologues: dog SH2D4B (95% identical), rabbit SH2D4B (93% identical), pig SH2D4B (93% identical), rat Sh2d4b (92% identical), mouse Sh2d4b (92% identical), guinea pig SH2D4B (87% identical), chimpanzee SH2D4B (77% identical), tropical clawed frog sh2d4b (65% identical), zebrafish sh2d4bb (61% identical), zebrafish sh2d4ba (56% identical), Caenorhabditis elegans F13B12.6 (33% identical). Paralogues in human: SH2D4A (45% identical), HSH2D (13% identical), SH2D2A (12% identical), SH2D7 (11% identical).
Diseases named in the same sentence as SH2D4B in open-access papers:
SH2D4B is named in the same sentence as 3 diseases in open-access papers, as found by Europe PMC text mining. Sharing a sentence is not in itself a finding about the gene and the disease. The quoted sentences say what the papers report.
Hearing impairment (1 paper, 2021). A decreased magnitude of the sensory perception of sound. "Five of the variants that have rare genotypes with large effects are at loci that have not been reported for any type of hearing impairment: FBF1, FSCN2, C10orf90, SH2D4B, and TBX2." (PMID 34108613, 2021).
SH2D4B also shares sentences with these, for which no sentence is quoted: breast carcinoma (1 paper); Tinnitus (1).